SPRR2F (small proline rich protein 2F)
Description:
Cross-linked envelope protein of keratinocytes. It is a keratinocyte protein that first appears in the cell cytosol, but ultimately becomes cross-linked to membrane proteins by transglutaminase. All that results in the formation of an insoluble envelope beneath the plasma membrane (By similarity).
Tractability: Antibody: its Gene Ontology location is reachable by antibodies, with high confidence.
Gene: Protein-coding gene on chromosome 1 (153,112,121 to 153,113,516, reverse strand). Ensembl gene ENSG00000244094.
Subcellular location: Cytoplasm
Pathways (Reactome):
Developmental Biology: Formation of the cornified envelope
Gene Ontology:
Biological process: epidermis development; keratinocyte differentiation
Cellular component: cornified envelope; cytosol; cytoplasm
Genetic constraint (gnomAD): Loss-of-function variants: 2 observed, 1.03 expected, observed/expected ratio (o/e) 1.93, 90% interval 0.51 to 1.94. That is too few expected variants to judge how well the gene tolerates losing a copy. Missense variants: 80 observed, 86.66 expected, observed/expected ratio (o/e) 0.92, 90% interval 0.77 to 1.11. Synonymous variants: 39 observed, 34.85 expected, observed/expected ratio (o/e) 1.12, 90% interval 0.87 to 1.46.
Diseases named in the same sentence as SPRR2F in open-access papers:
SPRR2F is named in the same sentence as 10 diseases in open-access papers, as found by Europe PMC text mining. Sharing a sentence is not in itself a finding about the gene and the disease. The quoted sentences say what the papers report.
endometrial carcinoma (3 papers, 2022 to 2025). A malignant tumor arising from the epithelium that lines the cavity of the uterine body. "In contrast, mice that lacked one copy of LKB1 in the endometrium (Sprr2f-Cre; Lkb1L/+) were weakly susceptible to endometrial cancer, with one out of 12 mice developing a focal endometrial tumor at ~600 days old." (PMID 35565271, 2022).
chronic kidney disease (1 paper, 2025). Impairment of the renal function secondary to chronic kidney damage persisting for three or more months. "In another study using a mouse model of chronic kidney disease, a protective function of the SPRR2F protein was observed by preventing oxidative damage." (PMID 40647632, 2025).
melanoma (1 paper, 2020). A malignant, usually aggressive tumor composed of atypical, neoplastic melanocytes. "Although there was no report of KRT2 and SPRR2F as a prognostic molecule of tumors, KRT2 and SPRR2F might function as promising biomarkers in melanoma." (PMID 33133157, 2020).
uterine tumors (1 paper, 2019). "In contrast, mouse model studies utilizing uterine tissue-specific Cre transgenes (e.g., Pgr-Cre, Ksp-Cre, Sprr2f-Cre) demonstrated that Pten mutation alone causes large uterine tumors (50, –52)." (PMID 30782821, 2019).
adenocarcinoma (1 paper, 2022). A common cancer characterized by the presence of malignant glandular cells. "Researchers previously reported that Cre-induced knockout of both LKB1 (mouse gene Stk11) alleles in the endometrium of mice (Sprr2f-Cre; Lkb1L/L) promotes the development of highly invasive adenocarcinomas in 100% of mice." (PMID 35565271, 2022).
SPRR2F also shares sentences with these, for which no sentence is quoted: tumor (3 papers); carcinosarcoma (1); childhood onset asthma (1); endometrial tumor (1); psoriasis (1).